CXCL5 (C-X-C motif chemokine ligand 5)
Diseases named in the same sentence as CXCL5 in open-access papers (continued):
Sharing a sentence is not in itself a finding about the gene and the disease.
tumor (continued). "In FOXM1 transgene model, elevated tumor formation was associated with persistent pulmonary inflammation, macrophage infiltration and increased expressions of CXCL5, CXCL1 and CCL3." (PMID 25788272, 2015). "Specifically, CXCL5 has been found to be important in mediating tumor-associated angiogenesis as well as in promoting growth, migration, and invasion of tumorigenic cell lines derived from NSCLC and other cancers." (PMID 24500664, 2014). "Subsequently, TDO2 activates the Kyn-AhR pathway, enhances glycolysis, promotes tumor cell proliferation, and secretes CXCL5 to attract immunogenic tumor-associated macrophages into the tumor microenvironment, thereby suppressing tumor immunity and influencing the progression of colorectal cancer." (PMID 40136551, 2025). "Similarly, RNF43 mutations reshape the tumor immune landscape through modulation of chemokine pathways such as CXCL5, further reinforcing immune evasion." (PMID 40303413, 2025). "In addition, tumor cell–derived CXCL5 has been shown to promote the recruitment of tumor-associated neutrophils into the lung parenchyma, thereby inducing CD8+ T cells exhaustion and facilitating ICI resistance." (PMID 41268560, 2025). "CAF were the major detectable source of CXCL5 in a patient tumor highly associated with cachexia." (PMID 41392310, 2025). "CXCL5 may serve as a diagnostic biomarker in cirrhotic patients for early HCC detection as well as for tumor progression." (PMID 36982370, 2023). "Few articles explored the association between tumor-derived CXCL5, CXCL6 and TAMs." (PMID 37865750, 2023). "In addition, CYLD regulates CXCL5 production by inhibiting NF-ĸB, thus affecting the migration of tumour-associated neutrophils." (PMID 35579924, 2022). "In addition, high expression of CXCL5 was found to be associated with poor tumor differentiation and poor survival of NSCLC patients." (PMID 36164607, 2022). "Furthermore, upregulation of CXCL5 expression parallels infiltration of immunosuppressive cells (e.g., M2 macrophages and tumor-associated neutrophils), leading to poor prognosis." (PMID 35664778, 2022). "We demonstrate that collagen-induced DDR1 activation in cancer cells is a major stimulus for CXCL5 production, resulting in the recruitment of tumor-associated neutrophils (TANs), the formation of neutrophil extracellular traps (NETs), and subsequent cancer cell invasion and metastasis." (PMID 34237033, 2021). "In addition, a direct association between CXCL5 expression and tumor growth was found in a mouse model of NSCLC." (PMID 34503058, 2021). "Besides, cancer-associated fibroblasts producing CXCL5 are involved in promoting PD-L1 upregulation in tumor cells." (PMID 34206815, 2021). "This implied a critical role of macrophage-derived CXCL5 as a novel mechanism underlying tumor development and may be a viable target for cancer therapeutics." (PMID 34745098, 2021). "Further, corroborating our findings, LECs when treated with CCA-CM also showed increased gene expression of CXCL5 (p ≤ 0.0001) in addition to increased expression of critical inflammatory agents implicated in tumor-associated lymphangiogenesis such as IL1B, IL6, IL8." (PMID 34831316, 2021). "Chemokines, such as CXCL-13 and CXCL-5, can cause B cells to aggregate at the tumor site." (PMID 35087829, 2021). "In addition, overexpression of CXCL5 was associated with lymphatic metastasis and tumor differentiation." (PMID 32632106, 2020). "Additionally, high levels of TGF‐β, Axl, and CXCL5 associate with advanced tumor stages and recruitment of neutrophils into cancer tissue of HCC patients." (PMID 30014484, 2019). "In additin, CXCL5 promoted metastasis by regulating tumor-associated angiogenesis." (PMID 25788272, 2015). "Moreover, we observed a significant clinicopathological association between CXCL5 expression and early tumor categories of CRC which matched the expression status of the corresponding primary tumors of the CRLM in our investigation." (PMID 18578857, 2008).
tumor (continued). "Moreover, YAP/TAZ mobilize myeloid-derived suppressor cells (MDSCs) and tumor-associated macrophages (TAMs) by upregulating various cytokines, including C-X-C motif chemokine 5 (CXCL5), C-C motif chemokine 2 (CCL2), macrophage colony-stimulating factor 1 (CSF1), and interleukin-6 (IL6)." (PMID 38067201, 2023). "In this review, we summarized the advances in research on CXCL5, including its dysregulation in different tumors and the mechanism associated with tumor behavior (formation of the immunosuppressive microenvironment, promotion of tumor angiogenesis, and metastasis)." (PMID 35978824, 2022). "For example, in pancreatic adenocarcinoma, NF-κB-driven expression of CXCL5 fosters tumor progression via recruitment of CXCR2+ myeloid-derived suppressor cells (MDSC) and tumor-associated neutrophils." (PMID 41516196, 2025). "To confirm the inhibition of tumor growth associated with decreased chemokine expression in Ccn1‐KO tumor, we focused on CXC chemokines, including CXCL1, CXCL3, and CXCL5, which bind to CXCR2, as well as CCL2 and CCL7, which bind to CCR2." (PMID 40287974, 2025). "CXCL5 has been also identified as a key chemokine driving the infiltration of mature pro-tumor neutrophils into lung cancer tissues." (PMID 40564191, 2025). "CXCL5 has also been studied as a therapeutic target for the prevention of tumor angiogenesis or as an enhancer of cancer drug efficacy." (PMID 41392310, 2025). "Several investigations have reported a strong association between CCL7, CCL13, CXCL5, and CCR9 and tumorigenesis as well as tumor development." (PMID 41465903, 2025). "Compared with control, Vox led to a slight decrease (not significant) of Cxcl1 expression in cancer cells, to a strong downregulation of Cxcl5 in total immune cells and macrophages, and to a modest upregulation of Cxcl2 in tumor macrophages." (PMID 40139833, 2025). "Mechanistically, KIF4A enhances the expression of the chemokine CXCL5, which recruits myeloid-derived suppressor cells (MDSCs) to the tumour microenvironment, thereby inhibiting antitumor immunity, facilitating immune evasion, and promoting tumour growth." (PMID 41361459, 2025). "The deletion of type I collagen in myofibroblasts leads to increased CXCL5 production in tumor cells, promoting MDSC aggregation, reducing T and B cell populations, and accelerating cancer progression." (PMID 40038745, 2025). "In the tumor region, DEGs included ECM-related genes such as MMP7, LCN2, chemokine CXCL5, and tumor markers CLDN4 and MUC4." (PMID 40303346, 2025). "We showed that Cxcl5 deletion significantly increased ferroptosis in 3D conditions, suggesting CXCL5 signaling as a potential target for the induction of tumor ferroptosis." (PMID 40050422, 2025). "In a non-small cell lung cancer (NSCLC) mouse model, CXCL5 gene knockout completely prevented neutrophil accumulation in the lung tissue, which in turn promoted the expansion and cytolytic function of tumor-specific CD8+ T cells." (PMID 40564191, 2025). "We then treated the 3D tumor cells with the conditioned media from these activated macrophages and investigated 3D tumor growth and CXCL5 expression." (PMID 40050422, 2025). "Beyond direct tumor cell signaling, CXCL5 secreted by fibroblasts, macrophages, Schwann cells, and mesenchymal stem cells can recruit CXCR2+ neutrophils, thereby enhancing immune evasion and metastatic niche formation." (PMID 40564091, 2025). "Tumor-derived CXCL5 recruits myeloid derived suppressor cells (MDSC), major contributors to the development of an immunosuppressive TME." (PMID 40176808, 2025). "CXCL5 facilitates neutrophil recruitment into the tumor microenvironment, where they impair CD8+T cell-dependent antitumor immunity." (PMID 41254689, 2025). "We confirmed that the 3D growth of tumor cells and the expression of CXCL5 were increased by the conditioned media from IFNγ + TNFα co-treated macrophages, similar to those of IFNγ + LPS stimulation." (PMID 40050422, 2025).
tumor (continued). "Autocrine CXCL5 regulates tumor stemness, while its paracrine action recruits THP‐1‐Mφ and promotes M2 polarization, thus underscoring the critical role of the CCL20/CXCL5 axis in the progressive tumor microenvironment." (PMID 40091357, 2025). "High expression of the ligands of Cxcr2, such as Cxcl1, Cxcl2, Cxcl3, and Cxcl5, was observed mainly in tumor cells, fibroblasts, chondrocytes, pericytes and osteoclasts among APM‐naïve cells." (PMID 40433925, 2025). "SLC6A14 and high CXCL5 demonstrated elevated expression in tumor cells compared to normal epithelial cells." (PMID 39670859, 2025). "Chemokines including CXCL5/CXCR2 are essential for MDSC recruitment in 4T1 BALB/c murine tumor models, while CCL1, CCL2, CCL5, GM-CSF, and G-CSF facilitate MDSC expansion and aggregation in the tumor milieu." (PMID 40909271, 2025). "CAF are a major cell population of the tumor microenvironment and it was discovered that inducible CXCL5 secretion from CAF contributes to cachexia, which can be mitigated by CXCL5 neutralization." (PMID 41392310, 2025). "CXCR2 is not only activated by CXCL1 but also by several other CXC chemokines, including CXCL2, CXCL3, CXCL5, CXCL6, and CXCL8, all of which are closely associated with cancer progression and the tumor microenvironment." (PMID 40490643, 2025). "Immunohistochemical analysis of the TA muscle showed that CXCR2 expression was upregulated in tumor bearing mice and downregulated by CXCL5 neutralization." (PMID 41392310, 2025). "CXCL5 has been reported to promote tumor progression by recruiting myeloid-derived suppressor cells and neutrophils, which establish an immunosuppressive microenvironment that facilitates angiogenesis and metastasis." (PMID 40749055, 2025). "Subsequently, we conducted spheroid formation assays to investigate the regulatory role of CXCL5 in tumor stemness characteristics." (PMID 40091357, 2025). "Prior research has indicated that the CXCL5/CXCR2 axis has the ability to enhance tumor development and angiogenesis, hence facilitating the infiltration and activation of host cells." (PMID 39670859, 2025). "Remarkably, we observed that SLC6A14 and CXCL5 were located in the same area within the ICC tumor cells, which aligns with the results obtained from the transcriptomics analysis." (PMID 39670859, 2025). "Hepatocellular carcinoma progresses because tumor-derived CXCL5 influences TAN recruitment to the tumor site." (PMID 40422244, 2025). "In the pre-metastatic niche, tumor-activated platelets secrete chemokines such as CXCL5 and CXCL7, which recruit granulocytes and remodel the local microenvironment to support incoming tumor cells." (PMID 40514754, 2025). "In corroboration of this result, we found reduced in vivo tumor growth of Cxcl5−/− Panc02 cells compared to WT after subcutaneous injection into mice." (PMID 40050422, 2025). "Collectively, tumor spheroids increased in size along with increase of CXCL5 expression in response to M1 macrophage-conditioned media." (PMID 40050422, 2025). "The CCL20/CXCL5 axis plays a crucial role in the interaction between TAMs and ATCSCs, establishing a progressive tumor microenvironment." (PMID 40091357, 2025). "We believe this comprehensive approach will provide the necessary validation and insight into the interaction between MRC1+ TAMs and CXCL5+SLC6A14+ tumor cells." (PMID 39670859, 2025). "It was observed that CXCL5 neutralization significantly reduced tumor signal flux at 3 weeks post-transplantation compared to control IgG." (PMID 41392310, 2025). "This overlapping expression of CXCL5 within the vimentin positive stroma was consistently observed in the patient tumor tissues." (PMID 41392310, 2025). "qPCR analysis of the tumor tissue indicated that the presence of CAF during tumorigenesis upregulated the expression of CXCL5, whereas the expression of CXCL1, 2, 3, 6, 7, 8, and IL-6 were not significantly affected." (PMID 41392310, 2025).
tumor (continued). "The results demonstrated that the Lv‐CXCL5‐ATCSCs group exhibited significantly higher tumor formation and tumor growth compared to the Lv‐vector‐ATCSC group." (PMID 40091357, 2025). "The upregulated chemokines can attract a diverse range of innate and adaptive immune cells, for example, CCL2 attracts tumor-associated macrophages, CXCL10/11 attracts CD8+ T cells, CCL20 attracts dendritic cells, and CXCL5 attracts neutrophils." (PMID 40689422, 2025). "SLC6A14 and CXCL5 demonstrated the co-location with panCK, indicating them as specific tumor markers." (PMID 39670859, 2025). "Immunostaining showed that CXCL5 was preferentially expressed in the CAF-rich stromal compartment of the tumor, with vimentin displaying an overlapping pattern of expression with the stroma." (PMID 41392310, 2025). "Unpaired differential expression analysis between the normal group and GBM group showed that CXCL5 expression was significantly higher in tumor tissues than in normal tissues (p < 0.05)." (PMID 38287266, 2024). "RT-qPCR results showed increased expression of CXCL2, CXCL3, and CXCL5 in tumor tissues after MC-LR exposure." (PMID 39273011, 2024). "Verteporfin, the inhibitor of YAP1, downregulated IL-6, CSF1-3, and CXCL5, which compel MDSCs in tumor." (PMID 38550587, 2024). "Immunofluorescence detection confirmed that the infiltration of macrophages increased in the tumor tissues of mice after CXCL5 knockout." (PMID 38287266, 2024). "They observed that the anti-VEGF drugs not only increased the content of CX3CL1 and CXCL5 in tumor vessels but also promoted the recruitment of neutrophils, resulting in the release of a large amount of the cytokine IL-10 to inhibit the adaptive immunity." (PMID 38534538, 2024). "It has also been found that CXCL5 promotes tumor angiogenesis in a CXCR2-dependent manner both in vitro and in vivo." (PMID 39835121, 2024). "Among all chemokines, CXCL5 stands out as one of the most important in the tumor microenvironment (TME)." (PMID 39034411, 2024). "Another neutrophil-recruiting chemokine Cxcl5, which is a downstream molecule of IL-17 signaling, dropped in tumor cells after Cyp51 knockout (Figure EV5A)." (PMID 38177537, 2024). "As the results showed that macrophages were educated by tumor cells and consequently generated more CXCL5, we further analyzed RNA-seq data." (PMID 38642131, 2024). "Increased levels of the chemokine CXCL5 suggest that astrocytic injury signals through CXCL5 to enhance tumor invasion and proliferation after GBM resection; however, these findings need further research." (PMID 39123366, 2024). "Through secretion of chemokines and effector molecules such as c-x-c chemokine ligand 5 (CXCL5), IL-1β, matrix metalloproteinases (MMPs), and collagen, CAFs contribute to immunosuppression and tumor angiogenesis." (PMID 38292868, 2024). "The correlation between CXCL5 and tumor immunoinfiltration was investigated using single sample gene set enrichment analysis (ssGSEA) of TCGA data." (PMID 38287266, 2024). "The SCID/NOD mice were injected with neutrophils and CD8+ T cells via the tail vein, followed by weekly injections of either anti-CXCL5 antibody or anti-PD-L1 antibody injections over a 3-week period subsequent to tumor formation using the A549 cell line." (PMID 39034411, 2024). "Mouse subcutaneous tumor models were also constructed through injection of cells with different CXCL5 expressions." (PMID 38287266, 2024). "Of note, administration of blocking antibodies against either CXCL5 or PD-L1 improved therapeutic efficacy, with the combination of CXCL5 and PD-L1 blocking antibodies demonstrating superior tumor control." (PMID 39034411, 2024). "CXCL5-induced fibronectin expression is consistent with a previous study on circulating tumor cells." (PMID 39765818, 2024). "For this purpose, the SCID/NOD mouse tumor-bearing model was employed to assess the CD8+ T cell-dependent antitumor effects of CXCL5 and PD-L1 neutralizing antibodies." (PMID 39034411, 2024).
tumor (continued). "Consistently, the combination of anti-CXCL5 and anti-PD-L1 treatment significantly inhibited tumor growth in vivo." (PMID 39034411, 2024). "Cell experiments and mouse subcutaneous transplanted tumor models were used to evaluate the role of CXCL5 in GBM." (PMID 38287266, 2024). "This possibly suggests that, while CXCL5 production is more isolated to tumor cells, CXCL2 appears mostly produced by stromal components, such as infiltrating immune cells." (PMID 38339310, 2024). "CXCL5 is upregulated in different tumor types and plays a role in promoting angiogenesis, lymphangiogenesis, attracting neutrophils and myeloid-derived suppressor cells (MDSCs), and facilitating primary tumor growth." (PMID 38365809, 2024). "Of note, in our study marginal mRNA expression of CXCL5 was observed in the epithelial/tumor cell cluster." (PMID 39249543, 2024). "Given that chemokines such as Cxcl5 are implicated in neutrophil attraction, we assessed expression of Cxcl5 and found significantly reduced expression in the epithelium of KPN KF tumours." (PMID 38168062, 2024). "For example, TGFB3-SDC4 and INHBA-TGFBR3 were found between POSTN+ fibroblasts and tumor cells and CXCL5-BDKRB2 and CCL7-ACKR2 were found between SPP1+ macrophages and tumor cells." (PMID 38519500, 2024). "YAP1 has been shown to contribute to inducing immunosuppressive TME by upregulating PD-L1 or stimulating cytokines such as CXCL5 from tumor cells to recruit tumor-infiltrating macrophages, myeloid-derived suppressor cells (MDSCs) and Tregs cells." (PMID 38659003, 2024). "The recruitment of the neutrophils in the TME takes place through the release of CXCL5 and CXCL6, with the subsequent transformation of the neutrophils in their pro-tumorigenic phenotype (N2 tumor-associated neutrophils—TANs)." (PMID 38791916, 2024). "Combined treatment with anti-CXCL5 and anti-PD-L1 antibodies significantly inhibits tumor growth in vivo." (PMID 39034411, 2024). "To elucidate the factors governing G-MDSC recruitment in CRNDE-induced HCC, we examined putative G-MDSC-recruiting chemokines, indicating that the expression of Cxcl3, Cxcl1, Cxcl5, and Ccl2 was significantly increased in upregulated Crnde tumor cells." (PMID 38169579, 2024). "CXCL5 triggers tumor metastasis and promotes the formation of an immunosuppressive microenvironment." (PMID 38287266, 2024). "Mesothelial cells undergo to mesothelial-mesenchymal transition induced by HGF secreted by OC cells, then CAMs promote the expression of pro-tumor factors such as IL-8 and C-X-C motif chemokine ligand 5 (CXCL5) to facilitate dissemination of OC cells." (PMID 39513610, 2024). "CXCL5 is generated from tumor cells in some types of cancers, stromal cells including macrophages, cancer-associated fibroblasts, and mesenchymal stem cells." (PMID 38642131, 2024). "To examine the effects of A2AR on CXCL5, neutrophils, and tumor growth in vivo, we constructed a mouse model bearing subcutaneous LLC tumors (1 × 106 cells per mouse)." (PMID 38642131, 2024). "Using a spontaneous murine model of melanoma, infiltration of PMN-MDSCs into primary tumors, mediated by CXCL5, was necessary for the tumor cells to disseminate through EMT." (PMID 38786066, 2024). "While CXCL-5 is a chemokine that recruits and activates leukocytes, it also promotes angiogenesis, tumor growth, and metastasis." (PMID 38812776, 2024). "DDR1 receptors on PDAC cells interact with collagens, inducing C-X-C motif chemokine ligand 5 (CXCL5) production, which in turn promotes the aggregation of tumor-associated neutrophils and the formation of neutrophil extracellular traps (NETs)." (PMID 38946426, 2024). "Levels of CTLA-8 (IL-17) and CXCL-5 decreased after vaccination, potentially indicating a reduction in tumor-promoting inflammation." (PMID 38812776, 2024).